CDK1 (cyclin dependent kinase 1)
Diseases named in the same sentence as CDK1 in open-access papers (continued):
Sharing a sentence is not in itself a finding about the gene and the disease.
cancer (continued). "In addition to the control of the cell cycle, CDK1 participates in many biologic processes involved in the growth of cancer cells, including DNA homologous recombination (HR) repair, the maintenance of cancer stem cell properties, mitochondrial bioenergetics, and tumor resistance." (PMID 37569750, 2023). "Therefore, all the analyses and experiments indicated that CR could induce the G2/M arrest by suppressing the PLK1/CDK1/Cyclin B axis, and ultimately inhibiting cancer cell growth." (PMID 37007025, 2023). "A systematic pan-cancer analysis shows that oncogene CDK1 is an immunological and prognostic biomarker, which may influence tumor immunity mainly by mediating the migration of immune cells to TME, and is positively associated with tumor mutational burden and microsatellite instability." (PMID 37077919, 2023). "Targeting CDK1 might provide opportunities for cancer prevention and therapy." (PMID 37311884, 2023). "Therefore, it is worthy to further investigate in the future whether human TCEAL7 regulates Cdk1 activity in cancer progression through the mechanism revealed in our present work, which may provide a novel strategy for cancer treatment." (PMID 37047236, 2023). "However, CDK1′s dysregulated activation and high expression confer resistance to chemo and radiation therapy and correlate positively with poor patient prognosis in breast, liver, colorectal, prostate, and other cancers." (PMID 38003585, 2023). "The differential overexpression of CDK1 gene in TCGA tumors lays the foundation for its potential as a tumor therapeutic target, and this differential overexpression involves more tumor types than other tumor targets, which validates its importance at the pan-cancer level." (PMID 36090896, 2022). "Targeting CDK1 may provide a novel and effective strategy for cancer immunotherapy." (PMID 35681641, 2022). "The oncogenic mutation HRASV12 has been found to induce activity of CDK1 and enhance protein O-GlcNAcylation, both of them having essential roles in induction of SOX2 expression and cancer stem cell properties in fibroblasts and cancer cell lines harboring RAS mutations." (PMID 36266723, 2022). "Therefore, CDK1 was recognized as a likely target for the treatment of cancer." (PMID 36184616, 2022). "However, the significance of CDK1 in the formation, progression, and prognosis of human pan-cancer remains unclear." (PMID 35681641, 2022). "However, abnormal CDK1 activity is a basis for cancer cell proliferation." (PMID 35406786, 2022). "However, current CDK1-based studies are limited to a single tumor type, and the role of the CDK1 gene in human cancers and the overall CDK1 tumor landscape are still unknown." (PMID 36090896, 2022). "Variations in the anti-mitotic activity and disruption of MT dynamics in numerous cancer cell types have been observed due to differences in the chemical carbocyclic structure of SLs, all of which trigger G2/M arrest via the upregulation of p-Cdk1 (Try 15) and cyclin B1." (PMID 35651747, 2022). "The results of the KEGG analysis suggested that CDK1 might be involved in different pathways such as mismatch repair, cell cycle, progesterone-mediated oocyte maturation, oocyte meiosis, DNA replication, HTLV-I infection, and pathways associated with cancer." (PMID 36090896, 2022). "Therefore, CDK1 has become one of the prospective targets for cancer therapy." (PMID 35806389, 2022). "Moreover, CDK1 regulates many cancers through multiple signaling pathways." (PMID 35774795, 2022). "Under normal growth conditions, binding of the cyclin B1 to CDK1 is necessary for CDK1 activation and initiation of its phosphorylation at threonine residue 161 (Thr 161), thereby commit the mitochondrial metabolism for adaptive cell cycle progression and resistance of cancer cells." (PMID 34064109, 2021).
cancer (continued). "While there has been much ongoing discussion surrounding the use of CDK1 inhibitors in cancer treatment to specifically perturb proliferation via cell cycle progression, our results make the novel suggestion that CDK1 targeting may be able to decrease the metastatic potential of cells." (PMID 33690598, 2021). "We found that four genes are highly expressed in HCC, among which four genes, CCNB1, CNB2, CDK1, and CYP3A4, are highly expressed in tumors, while CCNB1, CCNB2, and CDK1 are highly expressed in almost all cancer types, which may be involved in the important tumorigenesis or progression." (PMID 34337056, 2021). "Indeed, CDK1 overexpression was correlated with the progression of this type of cancer." (PMID 35011251, 2021). "Finally, the experiments using cancer cell lines and organoids confirmed that CDK1, CCNB, and CDC25A could induce LUAD proliferation and colony formation." (PMID 34446056, 2021). "Furthermore, our results suggest that CDK1-mediated BRD4 hyperphosphorylation contributes to BETi resistance, and that inhibition of CDK1 could synergistically work with BETi to more effectively kill cancer cells." (PMID 32575711, 2020). "The synergistic effect of the CDK1 inhibitor and BETi observed in our studies therefore provides the rationale for exploring aberrant CDK1 activation in cancer cells as a therapeutic target to overcome tumor BETi resistance and improve treatments for a diverse array of BRD4-associated cancers." (PMID 32575711, 2020). "The identification of p‐TFCP2L1 and CDK1 expression and co‐expression as predictive markers of cancer‐specific survival could open the prospect of developing p‐TFCP2L1/CDK1‐based immunohistochemical prognostic markers that could be easily applied in the clinic." (PMID 31709755, 2020). "Furthermore, a non-conducting Kv10.1 splice variant (E65, found in cancer cell lines), activates CDK1 when injected into Xenopus oocytes." (PMID 32854244, 2020). "Altering the modulation of the NMDAR by cyclin B/CDK1 may conduct to aneuploidy and cancer." (PMID 33184446, 2020). "Thus, whereas our observations are in line with the CHR-6494 anti-proliferative effects previously reported in human cancer lines and xenografted mice, they suggest that this drug could have other in vivo targets besides Haspin, such as CDK1." (PMID 32272587, 2020). "Notably, CDK1 inhibition significantly reduced the levels of genomic instability, underlining that premature entry induced by ATR inhibition drives genomic instability in PARP inhibitor‐treated BRCA2‐depleted cancer cells." (PMID 31529615, 2019). "In addition to CDK1, iASPP plays essential role in maintaining cancer cell proliferation." (PMID 29069733, 2017). "In addition to CDK1, iASPP has also been reported to be related to cancer cell proliferation." (PMID 29069733, 2017). "The intricate involvement of CDK1 in the cell cycle and DNA repair mechanisms suggests that CDK1 could be an important target in cancer treatment and more importantly, a previous study demonstrated that the effect of CDK1 inhibitor was selective towards cancer cells." (PMID 27050151, 2016). "In conclusion, CDK1 and MAD2L1 were adverse prognostic biomarkers for LUAD whose increased expression could render patients with LUAD a high risk of cancer recurrence and poor survival, suggesting that they might be applied as potential targets for LUAD treatment." (PMID 27835911, 2016). "Therefore, Cdk1 has been introduced as a promising gene for targeted therapy that could inhibit progress of the cell cycle in various cancers and induce apoptosis." (PMID 27385216, 2016). "In conclusion, the present study has shown that CDK1 and MAD2L1 are overexpressed in LUAD tissues and that its up-regulation may be indicative of poor survival rates and a higher risk for cancer recurrence, and it could have a potential role as a prognostic marker in LUAD patients." (PMID 27835911, 2016).
cancer (continued). "Hence, less CDK1-Cyclin B1 complex could be formed in cancer cells, leading to G2/M arrest and apoptosis, especially in HepG2 cells with less activated CDK1-Cyclin B1 complex." (PMID 27909289, 2016). "Thus, the use of small-molecule Cdk1 inhibitors could improve arrest at the G2-M boundary and prevent the entry of cancer cells into mitosis, thereby resulting in enhancement of apoptosis and tumor regression." (PMID 25511643, 2014). "It has been shown that NAMI-A inhibited the invasion and metastasis of cancer cells by arresting them at the G2/M stage and that it is a likely consequence of the accumulation of an inactive phosphorylated form of Cdk1, caused by the lack of Cdc25 phosphatase activity." (PMID 24507701, 2014). "However, it was reported that p21 activation inhibits p-CDK1 and results in G2/M arrest, suggesting that p-CDK1 may be regulated by alternative pathway mechanisms and different cancer types may be regulated by different pathways." (PMID 25275598, 2014). "First, SA of CDK1 may directly reflect higher cancer cell proliferation." (PMID 22108518, 2012). "In parallel to Cdk inhibitors, which have been extensively under clinical investigations, small molecule inhibitors against cyclin B1 could open up a new door for specific molecular cancer therapy by interfering with its protein stability, binding capacity to Cdk1 or its subcellular localization." (PMID 19113992, 2008). "IHC analysis confirmed cancer-specific enrichment of strong HSP60 positivity compared to benign tissues, a pattern absents for CDK1 and PLK1." (PMID 41522350, 2026). "Decreased expression of CDC25C, CDK1, and CCNB1 inhibited the transfer of cell cycle from G2 phase to M phase, resulting in the inhibition of cancer cell proliferation." (PMID 40313621, 2025). "Alsterpaullone, Avotaciclib, Fostamatinib, and Naringin demonstrated acceptable inhibitory effects on both CDK1 and WEE1 proteins, suggesting potential for synergistic control of cancer cell proliferation." (PMID 41009727, 2025). "Consistent with lucicebtide activity on C/EBPβ target genes in cancer cells, ID2, BIRC3, CyclinA2 and CDK1 were significantly downregulated in lucicebtide-treated M2-cells." (PMID 40103809, 2025). "Western blot experiments confirmed the reduced expression of CDK1, CCNB1, and PLK1 in KIF2C knockdown cancer cells at the protein level." (PMID 41333555, 2025). "CCNB1, PLK1, CDK1, BUB1B, AURKA, and NDC80 are genes involved in various stages of the cell cycle process, which is crucial from a cancer perspective." (PMID 40287845, 2025). "We examined the expression levels of cyclin B, Cdk1, cyclin D1, PCNA, JAK1, STAT3, and other cancer pathway components." (PMID 40350446, 2025). "For other genes, the proportion changes in different cell types expressing BIRC5, CDK1, AURKA, E2F1, and KIF2C are remarkably similar to the overall proportion changes in different cell types during cancer progression." (PMID 39859485, 2025). "We performed a head-to-head comparison of N-acetylgalactosamine (GalNAc)-conjugated small interfering RNA (siRNA)-mediated inhibition of five genes (CDK1, PD-L1, CTNNB1, SMYD3, ANLN) to prevent cancer in four distinct autochthonous HCC mouse models." (PMID 40704506, 2025). "AOH1160 repressed the expression of CDK1, CCNB1, CDK2 and CCNE2 to arrest the cell cycle at G2/M phase, thus blocking the promotion of cancer cell mitosis." (PMID 40313621, 2025). "This comprehensive inquiry aimed to unravel the intricate expression patterns of CDK1 and DTL across these diverse cancer studies." (PMID 39567714, 2024). "It was found that CDK1 overexpression in adrenocortical carcinoma cell (ACC) lines locked ACC cells at the G2/M checkpoint by interacting with UBE2C and AURKA/B, promoting cancer cell proliferation and inducing epithelial mesenchymal transition (EMT)." (PMID 39830349, 2024).
cancer (continued). "Other reviews have highlighted the impact of CDK1 inhibitors in breast cancer, emphasizing that inhibiting HOP phosphorylation would be promising to decrease cancer cell progression." (PMID 39433125, 2024). "By integrating microarray and RNA sequencing datasets, we found that CDK1, CCNA2, and CCNB1 were significantly upregulated in OS samples than non-cancer samples." (PMID 38164289, 2024). "It is reported to have direct CDK1 enzyme inhibition (Ki of 35 nM) and a modest cell activity of 9 μM (for complete inhibition of cell cycle at HCT116 and HeLa cancer cell lines)." (PMID 39184376, 2024). "This was evidenced by the reduction in phosphorylation levels of CDK1/2/3 and Rb proteins in sh-DNMT1 cancer cells." (PMID 38755637, 2024). "Gene interaction network analysis of DEGs indicated top significant subnetworks related to a number of cancer-related pathways and hub genes, including E2F, PI3K, p38 MAPK, JNK, Rb, CDK1, and MAP2K." (PMID 39181873, 2024). "Accumulating evidence suggests that CKS2 is an oncoprotein that promotes cancer tumorigenicity and progression, and that CKS2 levels in PTC correlate with the expression of its downstream genes, including cyclin B1 and CDK1." (PMID 39188686, 2024). "Cyclin-dependent kinase 1 (CDK1), a protein kinase involved in cell division, is dysregulated in various cancer types." (PMID 38273337, 2024). "Overexpression of AURKA/B, CDK1, and PLK1 has been reported in several malignant tumors, including HCC." (PMID 38672246, 2024). "Since CDK1, CHEK1, KIF11, PLK1 and TTK was significantly elevated with cancer progression in LUAD and exhibited excellent binding performance with 6-MDS, they were chosen for further validation." (PMID 38783288, 2024). "The phosphorylation of some well-known cancer driver genes, including RB1 at T373, CDK1 at T161, and MCM at S27, has been identified exclusively in tumors." (PMID 39039072, 2024). "Most of these genes were cell cycle-related genes, including CHEK1, CDK1, RUVBL2, PSMD14, SUPT5H, RBX1, and AURKA, across 28 cancer types." (PMID 38972884, 2024). "A reduction in the phosphorylation levels of CDK1/2/3 and Rb was observed in sh-DNMT1 cancer cells compared to sh-NC cells, confirming the additional inhibition of CDK2-Rb signal transduction." (PMID 38755637, 2024). "siRNA-mediated knockdown of c-Fos in NQO1-expressing cancer cells increased CDK1 kinase activity, whereas overexpression of CKS1B decreased c-Fos-mediated enhancement of CDK1 kinase activity in these cells." (PMID 36793872, 2023). "To corroborate this result, we also evaluated the expression of CDC25A, CDK1 and CCNB1, the most important cell cycle regulatory proteins involved in cancer progression." (PMID 37504902, 2023). "The results showed that CCNA2, CDK1, KIF11, MKI67, and PLK1 were significantly and positively correlated with CEP55 in pan-cancer." (PMID 37887301, 2023). "Using Timer 2.0, we found that PLK1, CDK1, CCNB1, and CCNB2 were upregulated in different cancer types compared with normal samples from the TCGA data set." (PMID 37007025, 2023). "Since CDC25C is the link among CDK1, CCNB, and PLK1, and the expressions of CDC25C among ten cancer cell lines are also downregulated, we added CDC25C for the experiment validation step." (PMID 37007025, 2023). "We further provide preclinical evidence demonstrating that targeting CDK1/PIN1 axis is a common and effective approach to suppress tumor progression of TNBC and other cancers harboring wild-type VHL including TNBC." (PMID 36813923, 2023).
cancer (continued). "In this study, we reveal the cyclin-dependent kinase 1 (CDK1) and peptidyl-prolyl cis-trans isomerase NIMA-interacting 1 (PIN1) as two previously uncharacterized regulators of pVHL stability in multiple cancer types harboring wild-type VHL including TNBC." (PMID 36813923, 2023). "The results showed that HDAC3 silencing reduced the phosphorylation of CDK1 Y15 and STAT3 Y705 followed by reduction of CD44 and Sox2, which resulted in the impairment of cancer cell stemness." (PMID 37743465, 2023). "The hit list in our screen reassuringly contained many well-known cancer genes such as PCNA, CDK1 and PLK1, further demonstrating the validity of the screen results." (PMID 37161535, 2023). "Out of these, AURKA, TOP2A, CDK1, and BUB1 were also included in the list of most frequent top NMF genes across the 24 cancer types." (PMID 37973839, 2023). "According to the Oncomine and TCGA data, PLK1, CDK1, and CCNB are known to be elevated in different cancer types." (PMID 37007025, 2023). "Based on these results, CDK1, CDK2, CDK4, CDK5, and CDK7 are the top 5 CDKs that are highly expressed in cancer tissues compared to normal tissues." (PMID 37311884, 2023). "CDK1 is significantly higher in 17 out of 24 or 70.8% of the cancers listed and CDK2 and CDK7 are higher in 16 out of 24 or 67% of the cancers listed." (PMID 37311884, 2023). "On the other hand, in HMGB1-stimulated HCT116 cancer cells, C6 was revealed to suppress the activation of ERK1/2, CDK1, and AKT and the down-regulation of anti-apoptotic XIAP but not c-IAP1, c-IAP2, and Bcl-xL and up-regulate pro-apoptotic Bax and caspase-3/7." (PMID 35408786, 2022). "CDK1 had been found highly expressed in HCC tissues, and CDK1 mediated nuclear accumulation of apoptin and participated apoptosis in cancer." (PMID 35193513, 2022). "At present, many studies have shown that the hub genes CDC20, CDK1, BUB1, CCNB1, and BUB1B identified in our PPI network are involved in cancer progression." (PMID 35664322, 2022). "This showed that CDK1 can substitute for CDK2 in triggering the S-phase, while, in cancer cells, CDK2–cyclin B complexes allow for the onset of mitosis in the absence of CDK1." (PMID 35805103, 2022). "When comparing CDK1 expression values between normal and tumor samples in LUAD, the expression value was significantly increased in cancer samples (p-value < 2.2 × 10−16)." (PMID 35885905, 2022). "We found that CDK1 expression was positively correlated with TMB in 15 cancers and with MSI in five cancers." (PMID 36090896, 2022). "Targeted regulation of cyclin-dependent kinase 1 (CDK1), KIF11, and AURKA proteins blocked the cell cycle and increased the number of mitotic catastrophes, resulting in senescence and death of 4T1 cancer cells." (PMID 35963853, 2022). "Further studies have shown that the combined inhibition of CDK1 and BRD4 can overcome the resistance of cancer to BETis to more effectively kill cancer cells related to BRD4-dependent survival." (PMID 35402244, 2022). "Cyclins and cyclin-dependent kinases (CDKs) are major effectors of the cell cycle with key role in cancer where our data shows downregulation of key cell-cycle proteins such as cyclin D1 and Geminin and mRNA levels of CCNE1, CCNF, CDK1, CDK2 and CDK5." (PMID 35902556, 2022). "In summary, these data indicated that CDK1 expression is up-regulated in LUAD and related to the development of cancer." (PMID 35406786, 2022). "The mRNA expression of both genes CDK1 and HSP90AA1 were significantly upregulated in both the datasets, LUAD and LUSC, between lung cancer and non-cancer patients." (PMID 35330393, 2022). "The combination of CDK1/ERK2/PLK1 and CEP55 inhibitors is a rational strategy to impair cell cancer division and merits further investigation." (PMID 35517890, 2022). "We selected five genes (P57, CDK1, CDH2, E2F1 and BIK) that are quite relevant to cancer cell proliferation and apoptosis 24-28." (PMID 35371316, 2022).